METTL3 (methyltransferase 3, N6-adenosine-methyltransferase complex catalytic subunit)
Diseases named in the same sentence as METTL3 in open-access papers (continued):
Sharing a sentence is not in itself a finding about the gene and the disease.
cancer (continued). "Carbon ion radiotherapy elevates METTL3 levels and its associated m6A modifications in NSCLC cells, influencing cancer cell migration and invasion." (PMID 39802639, 2025). "For example, METTL3, as an m6A writer, significantly influences multiple cancers by dynamically regulating immune cell infiltration." (PMID 40867324, 2025). "The m6A methyltransferase METTL3 is a key regulator of RNA m6A modification, which plays a critical role in cancer development." (PMID 40651967, 2025). "Here, the results show that m6A methyltransferase METTL3 regulates cilia length in cancer cells via HDAC6‐dependent deacetylation of axonemal α‐tubulin, thereby controlling cancer development." (PMID 39535388, 2025). "METTL3 depletion in vehicle-treated cells resulted in ten KEGG pathways enriched in genes higher in siSCR compared with siMETTL3 including Pathways in cancer (hsa05200) and Signalling pathways regulating pluripotency of stem cells (hsa04550)." (PMID 41310336, 2025). "This small molecule inhibitor, STM2457, is highly selective for the S-adenosyl methionine (SAM) binding site of METTL3 and was found to reduce m6A levels and have promising effects in several cancer contexts." (PMID 41310336, 2025). "By catalyzing the addition of a methyl group to RNA molecules, METTL3 influences mRNA stability, translation efficiency, and splicing patterns, ultimately impacting gene expression networks that drive cancer development." (PMID 40177651, 2025). "Collectively, these findings suggest that METTL3 is a promising therapeutic target for radiosensitization across various cancer types." (PMID 40823093, 2025). "In contrast, in cell lines in which METTL3 expression was downregulated by a short hairpin RNA (shRNA), its function in cancer was effectively inhibited." (PMID 40356909, 2025). "Studies have shown that METTL3 promotes cancer cell stemness and survival and enhances resistance to the chemotherapeutic drugs 5-FU and OXA by upregulating Sec62 and activating the Wnt/β-catenin signaling pathway." (PMID 40356985, 2025). "This marks a major milestone in targeted cancer therapy with the development of METTL3-specific inhibitors as a new therapeutic strategy." (PMID 40823087, 2025). "Our previous works and others elucidated that GCS modulates the β-catenin signaling pathway to up-regulate the expression of ABCB1, FGF2, and METTL3 in cancer cells." (PMID 40507922, 2025). "For instance, YTHDF2 modulates the m6A methylation of OCT4 mRNA to promote the cancer stem cell phenotype and cancer metastasis; while METTL3 promotes HCC progression through an m6A-YTHDF2-dependent post-transcriptional silencing of SOCS2." (PMID 39799112, 2025). "Elevated METTL3 expression has been observed in various tumors, contributing to increased m6A modification on target genes and promoting cancer progression." (PMID 41390674, 2025). "We further examined the cancer‐promoting effect of the METTL3/HDAC6 axis in cancer progression in vivo." (PMID 39535388, 2025). "Other small molecule inhibitors that target METTL3/METTL14 were tested in different cancer cell lines." (PMID 40483535, 2025). "Dysregulation of METTL3 can promote or inhibit cancer progression through distinctive mechanisms in different cancers." (PMID 40830264, 2025). "Multiple studies have demonstrated that methyltransferase like 3 (METTL3) mediated m6A modification can regulate oncogene expression and promote cancer progression through RNA processing, splicing, degradation, and translation." (PMID 40175350, 2025). "Further, small molecule METTL3 inhibitors are also gaining increasing attention in cancer therapy due to their potential to modulate cellular m6A functions." (PMID 40219966, 2025). "METTL3, a vital component of the m6A methyltransferase complex, is involved in multiple types of cancers." (PMID 40727611, 2025). "The Cancer Genome Atlas Program (TCGA) database and immunohistochemistry validated the role of the METTL3/SLC7A11 axis in cancer progression." (PMID 39800682, 2025).
cancer (continued). "Researchers are actively investigating the downstream effects of METTL3 dysregulation, exploring its impact on specific signaling pathways and biological processes that contribute to cancer growth and metastasis." (PMID 40177651, 2025). "This study demonstrated that extracellular vesicles derived from M2 macrophages suppress METTL3 expression in cancer cells via miR-21-5p." (PMID 41583453, 2025). "As a key enzyme responsible for m6A modification, METTL3 has attracted considerable attention for its functions across various cancer types." (PMID 40678060, 2025). "Given the broad oncogenic roles of METTL3 in cancers, it is very interesting that METTL14 exerts antitumor functions in an m6A-depnedent manner in most tumors, which brings our attention to understand their roles as a whole MTC." (PMID 40734692, 2025). "Further, the expression of YY1 was significantly positively correlated with the expression of METTL3 in clinical cervical and breast cancer patients from TCGA." (PMID 39800682, 2025). "METTL3 promotes cancer stem-like cell (CSC) phenotype in oral squamous cell carcinoma(OSCC) by targeting SALL4 through the Wnt/β-catenin signaling pathway." (PMID 41256854, 2025). "METTL3, with a length of 580 amino acids, a key component of MTCs, is widely involved in cancer progression and therapeutic targeting." (PMID 40510136, 2025). "Most METTL3-related research predominantly focuses on its methyltransferase activity in cancer, however, the precise molecular mechanisms of protein degradation are unclear." (PMID 40175350, 2025). "In most cases, METTL3 has been reported as an oncogene that promotes the initiation and development of various cancers." (PMID 39800682, 2025). "Previously, METTL3‐catalyzed m6A in HMBOX1 mRNA was shown to induce genomic instability in cancers by disrupting telomere homeostasis." (PMID 40008841, 2025). "Although many studies identified the oncogenic roles of METTL3 in many cancers, some groups showed the opposite phenotypes of METTL3 in the same cancer types with a distinct mechanism." (PMID 40734692, 2025). "METTL3-mediated m6A modification regulates cancer stem cell characteristics, proliferation, invasion, and metastasis in cancer." (PMID 41515964, 2025). "It has been reported that METTL3 binds to about 22 % of all m6A modified sites in transcriptome, indicating the non-m6A related mechanism remains crucial in cancer cells." (PMID 40734692, 2025). "In COAD cells, NSUN6 up-regulates METTL3 expression and mediates its m5C modification, facilitating cancer progression." (PMID 41256854, 2025). "Previous studies have implicated METTL3 and miR-146a-5p in the regulation of EMT markers across various cancers." (PMID 40338154, 2025). "STM2457 is a small molecule that selectively inhibits METTL3, with potential therapeutic applications for cancer treatment." (PMID 41238564, 2025). "As a well-known m6A “writer”, METTL3-mediated m6A modification is closely correlated with RNA metabolism, including lncRNAs, in cancer." (PMID 40510136, 2025). "The m6A methyltransferase METTL3 was upregulated during cancer cell ferroptosis and facilitated erastin-induced ferroptosis by enhancing mitochondrial ROS." (PMID 39800682, 2025). "The therapeutic potential of targeting METTL3 in cancer is gaining traction, with inhibitors such as STM2457 and RSM3 showing promise in preclinical models." (PMID 40651967, 2025). "RNA methyltransferase inhibitors, including METTL3 inhibitors, are being investigated for their role in cancer treatment." (PMID 41335282, 2025). "In recent years, a number of studies have found that METTL3 is involved in cancer development as a cancer promoting factor." (PMID 41256854, 2025).
cancer (continued). "This suggests that METTL3’s involvement in HIF-1 signaling extends beyond cancer, influencing immune and hematopoietic responses under toxic conditions." (PMID 40102715, 2025). "METTL3 can promote cancer cell proliferation and anti-apoptosis by regulating various targets and pathways, including miRNAs and non-coding RNAs, which are critical for BCa." (PMID 40678060, 2025). "Collectively, our study sheds light on the previously neglected role and function of the m6A methyltransferase METTL3 in cilia elongation and cancer development." (PMID 39535388, 2025). "METTL3 is also overexpressed in breast, lung, liver, colon, colorectal, and prostate cancer, contributing to the growth, proliferation, and invasion of cancer cells." (PMID 40483535, 2025). "Accumulating evidence has shown that METTL3 regulates ferroptosis in various cancers by modulating key factors such as SLC7A11, GPX4 and FSP1." (PMID 40175350, 2025). "In cancer, aberrant expression of m6A-modifying enzymes such as METTL3 and FTO drives malignant phenotypes, including cell proliferation, metastasis, metabolic reprogramming, and immune evasion." (PMID 41446042, 2025). "One such molecule, METTL3, is a key methyltransferase responsible for m6A modification and plays a crucial role in cancer development and progression." (PMID 40678060, 2025). "In comparison, METTL3, another core m6A writer, has been shown to play predominantly oncogenic roles in most cancers and also critically regulates immune responses." (PMID 41322419, 2025). "As an RNA methyltransferase, METTL3 has attracted much attention in cancer research in recent years." (PMID 40678060, 2025). "We evaluated the potential mechanisms responsible for erastin-regulated expression of METTL3 in cancer cells." (PMID 39800682, 2025). "Targeting the m6A machinery-including FTO, a demethylase-or METTL3-has become a possible approach for cancer treatment." (PMID 40530256, 2025). "Clinical trials targeting METTL3 are significant in cancer therapy due to the role of METTL3 in RNA methylation and gene expression regulation." (PMID 41515964, 2025). "For example, overexpression of the m6A methyltransferase METTL3 promotes cancer cell proliferation and migration in HCC, leading to poor prognosis in patients with HCC." (PMID 39438075, 2024). "METTL3 plays an essential role in cancer mainly by affecting RNA splicing, export, localization, translation, stability." (PMID 39497721, 2024). "In HCC cancer stem cells (CSCs), methyltransferase 3, N6-adenosine-methyltransferase complex catalytic subunit (METTL3)-mediated m6A modification of Frizzled-10 (FZD10) mRNA resulted in FZD10 upregulation." (PMID 39682130, 2024). "Recent studies have uncovered the crucial role of DGCR8 in pri‐miRNA processing and how it often necessitates METTL3 or METTL14 in different cancer types." (PMID 38380598, 2024). "METTL3, the key component of the methyltransferase complex, can play different roles in multiple types of cancer." (PMID 39095708, 2024). "Often working together, the METTL3/METTL14 complex plays an oncogenic role in various cancers, including breast, kidney, and liver cancer, but has an anti-cancer effect in neuroblastoma." (PMID 39155349, 2024). "To date, numerous studies conducted on patients’ material, as well as in vitro/in vivo functional and mechanistic studies, point out the significant role of the METTL3 gene in various types of cancer, including HNSCC." (PMID 38966069, 2024). "While the impact of METTL3 on cancer cells has been extensively reviewed, its roles in TME and anti-cancer immunity have not been comprehensively summarized." (PMID 38322265, 2024). "Given the crucial role of METLL3 in m6A methylation, the biological functions of METTL3 in the process of cancer including HCC have been widely investigated." (PMID 38545555, 2024).
cancer (continued). "Most cancer studies on the role of METTL3 have focused on regulating the oncogenic effects of its downstream factors, whereas upstream regulators that lead to abnormal METTL3 expression have received little attention." (PMID 38166703, 2024). "Numerous studies have revealed that METTL3-induced m6A directly upregulated expression of various glycolytic enzymes in different cancers." (PMID 38531882, 2024). "METTL3 is a risk factor for SOC and a core m6A methyltransferase that plays critical roles in various cancers." (PMID 38895621, 2024). "In pancreatic cancer, METTL3 increases the expression of PD-L1 by upregulating the expression of lncRNA MALAT1 in cancer cells." (PMID 39372415, 2024). "A mass of evidences showed that overexpressed METTL3 widely participated in the acquisition of various therapeutic resistance in many cancer types." (PMID 38531882, 2024). "The m6A methylation process mediated by METTL3 affects the different stages of mRNA metabolism and the biological production of long non-coding RNAs, circRNAs and miRNAs in many cancers." (PMID 38370374, 2024). "METTL3 plays a crucial role in cancer progression, and METTL3 inhibition has attracted the attention of pharmaceutical companies." (PMID 38166703, 2024). "Yet, recent discoveries have revealed that METTL3 can undergo mislocalization to the cytoplasm of cancer cells, where it boosts the translation of particular oncogenes." (PMID 38444581, 2024). "Conversely, elevated levels of METTL3 predominantly facilitate cancer occurrence and progression in the female reproductive system." (PMID 38332508, 2024). "For other cancers, the bacterium Fusobacterium nucleatum (F. nucleatum) can downregulate METTL3 while reducing the level of m6A modification, inducing CRC metastasis." (PMID 38711100, 2024). "This review aims to consolidate our current understanding of how m6A and METTL3 shape translation regulation in the realm of cancer biology." (PMID 38444581, 2024). "METTL3 expression is upregulated in PCa cell lines, and knockdown of METTL3 induces apoptosis in cancer cells." (PMID 38166703, 2024). "For example, in various cancers, METTL3 has been shown to promote the translation of specific oncogenes, thereby promoting tumorigenesis and cancer progression." (PMID 39728691, 2024). "METTL3, a major regulator of RNA m6A methylation, has been shown to be oncogenic in various cancers." (PMID 38370374, 2024). "Researchers also investigated the LLPS behavior of METTL3 cancer mutants, including R508H, R415C, and E516K, finding that R415C and E516K mutants fail to undergo LLPS separation." (PMID 39006762, 2024). "This unravels that METTL3's involvement extends beyond catalyzing m6A to participating in the postmethylation regulation of target mRNA, thus playing a role in cancer development." (PMID 38706740, 2024). "In most cases, METTL3 has been reported as an oncogenic gene that promotes the occurrence and development of various cancers, including hematopoietic malignancies and solid tumors, by depositing m6A modifications on key transcripts." (PMID 38281945, 2024). "METTL3 controls extracellular vesicle (EV)‐mediated transfer of drug resistance to non‐resistant cancer cells." (PMID 39661414, 2024). "For example, METTL3 and METTL14 have been implicated as overexpressed and act as oncogenes in most cancer types." (PMID 38589454, 2024). "Targeting METTL3 based on its diverse functions holds promise for developing precision cancer therapies." (PMID 38545841, 2024). "Since the discovery of the efficacy of the first inhibitor targeting METTL3, novel drugs aimed at epitranscriptomic targets have been developed to enhance treatments for cancer and various diseases." (PMID 38476632, 2024).
cancer (continued). "Pan-cancer analysis showed that METTL3 expression was up-regulated in a variety of cancers, and higher METTL3 expression levels were significantly associated with poorer overall survival in ACC, KICH and LIHC, and poorer DFS in ACC, CESC, HNSC, KICH and LIHC." (PMID 39289775, 2024). "The authors conclude that the anti-cancer effects of metformin can be attributed to its effect on the regulation of the miR-483-3p/METTL3/m6A/p21 pathway." (PMID 39796103, 2024). "Another promising candidate is STM2457, a highly selective METTL3 inhibitor with minimal effects on other methyltransferases, indicating its potential as a targeted cancer therapy." (PMID 39098905, 2024). "The m6A reader IGF2BP2 recognizes the modification and increases its levels by inhibiting degradation and thus facilitating the metastatic spread of cancer.[36a] Circular RNA has been proposed as another target for METTL3 in the metastatic spread of CRC." (PMID 39661414, 2024). "Recent studies have identified METTL3 as an oncogene in GC, promoting proliferation, migration, invasion, and metastasis of cancer cells." (PMID 39357829, 2024). "Targeting METTL3 also decreases glucose uptake, impairs cell proliferation, and inhibits cancer growth, providing novel perspectives for CRC therapeutic strategies." (PMID 38721006, 2024). "METTL3 addresses the energy and biosynthetic needs of the ongoing proliferation and metastasis of malignant tumors by regulating glycolysis-related enzymes." (PMID 39678510, 2024). "Our study paves the way for future studies on the mechanistic understanding of how METTL3 can be guided to specific genomic locations by MYCN or other oncogenic transcription factors to drive m6A modification in cancers." (PMID 39528654, 2024). "METTL3 promotes cancer cell proliferation and anti-apoptosis by regulating various targets and pathways, including miRNAs and non-coding RNAs, which are essential for PCa." (PMID 38166703, 2024). "The study of m6A modulators, including METTL3 inhibitors, has gained increasing attention due to their roles in regulating gene expression in cancer cells." (PMID 38545841, 2024). "In this review, in addition to the m6A-dependent mechanisms regulating translation in cancer, we describe the current understanding of the cytoplasmic function of METTL3." (PMID 38444581, 2024). "Abundant evidence demonstrates that METTL3, as the primary m6A writer, plays imperative roles in various types of cancers, by affecting both cancer cells themselves and the surrounding immune cells and non-immune cells in TME." (PMID 38322265, 2024). "Both upregulation and downregulation of METTL3 impact cancer sensitivity to chemotherapy, further highlighting the intricate role of m6A regulators." (PMID 38545841, 2024). "Rather than playing a unique role, research has proved that the role of m6A and METTL3 in cancer is context-dependent." (PMID 38444581, 2024). "While the potential for cancer treatment through targeting METTL3 and METTL16 has been extensively demonstrated, it is important to note that these genes are essential for cell survival." (PMID 39333489, 2024). "Ultimately, our goal is to provide critical insights into the interplay between m6A, METTL3 and translational regulation in cancer, offering a deeper comprehension of the mechanisms sustaining tumorigenesis." (PMID 38444581, 2024). "Currently, STC15 is undergoing Phase 1 trials, which makes a significant stride in the exploration of advanced METTL3 inhibition strategies and their potential applications in cancer therapeutics." (PMID 38809498, 2024). "In cancer cells, m6A writer complex (METTL3/METTL14/WTAP)‐mediated modification of c‐Myc mRNA is protected from YTHDF2‐mediated degradation by MSI2 with c‐Myc overexpression." (PMID 39661414, 2024). "For example, the EMT-TF Snail, which drives aggressive cancer traits, is stabilized by m6A modification mediated by METTL3 and IGF2BP2." (PMID 39695216, 2024).